CMTM7 (CKLF like MARVEL transmembrane domain containing 7)
Synonyms: CKLFSF7; FLJ30992
Tractability: Antibody: UniProt predicts a signal peptide or a membrane-spanning region; the Human Protein Atlas places it where antibodies can reach.
Gene: Protein-coding gene on chromosome 3 (32,391,686 to 32,483,067, forward strand). Ensembl gene ENSG00000153551.
Subcellular location: Membrane
Subcellular location (Human Protein Atlas): Plasma membrane
Gene Ontology:
Molecular function: protein binding
Cellular component: membrane
Genetic constraint (gnomAD): Loss-of-function variants: 7 observed, 17.33 expected, observed/expected ratio (o/e) 0.4, 90% interval 0.23 to 0.76. The upper end of that interval is the gene's LOEUF score, 0.76, which puts it in group 3 of 6, group 1 being the genes least tolerant of losing a copy. Missense variants: 193 observed, 213.03 expected, observed/expected ratio (o/e) 0.91, 90% interval 0.81 to 1.02. Synonymous variants: 87 observed, 83.95 expected, observed/expected ratio (o/e) 1.04, 90% interval 0.87 to 1.24.
Homologues: Orthologues: chimpanzee CMTM7 (100% identical), macaque CMTM7 (97% identical), dog CMTM7 (83% identical), guinea pig CMTM7 (81% identical), mouse Cmtm7 (79% identical), rabbit CMTM7 (68% identical), pig CMTM7 (66% identical), rat Cmtm7 (63% identical), zebrafish cmtm7 (49% identical). Paralogues in human: CMTM4 (25% identical), CMTM6 (23% identical), CMTM8 (19% identical), PLLP (18% identical), MALL (16% identical), CMTM1 (15% identical), PLP2 (15% identical), CMTM3 (14% identical), MAL (14% identical), MAL2 (14% identical), CKLF (13% identical), CMTM5 (13% identical), and 2 more.
Diseases named in the same sentence as CMTM7 in open-access papers:
CMTM7 is named in the same sentence as 26 diseases in open-access papers, as found by Europe PMC text mining. Sharing a sentence is not in itself a finding about the gene and the disease. The quoted sentences say what the papers report.
breast carcinoma (10 papers, 2019 to 2025). "Taken together, these results showed that CMTM7 was downregulated in breast cancer tissues and cell lines, and the CMTM7 loss was related to a poor prognosis." (PMID 36829181, 2023). "However, the underlying mechanism of CMTM7 in breast cancer still needs further investigation." (PMID 36829181, 2023). "CMTM7 can interact with Catenin Alpha 1 to regulate Wnt/β-catenin signaling to inhibit breast cancer progression and be a novel target for breast cancer." (PMID 38223763, 2024). "The RT-qPCR analysis of CMTM7 mRNA expression levels in 30 paired clinical tissues revealed that breast cancer tissues had significantly lower CMTM7 mRNA levels than paired normal tissues." (PMID 36829181, 2023). "In our study, we investigated the methylation of CMTM7 CpG island through BSP sequencing among breast cancer cells and tissues." (PMID 36829181, 2023). "In the current study, we revealed a feedback loop formed by miR-182-5p/CMTM7/CTNNA1/CTNNB1/TCF3 in breast cancer progression." (PMID 36829181, 2023). "The results indicated that CMTM7 was hypermethylated in breast cancer, leading to the CMTM7 downregulation." (PMID 36829181, 2023). "The expression level of CMTM7 in breast cancer cells and tissues was detected by qRT-PCR and western blot, and the methylation of CMTM7 promoter was detected by BSP sequencing." (PMID 36829181, 2023). "We demonstrated that a considerable part of PD‐L1 that is overexpressed during the EMT process is regulated via CMTM6 and CMTM7 in breast cancer cells." (PMID 35575054, 2022). "The LinkedOmics database predicted 1702 genes related to the expression of CMTM7 in breast cancer tissues in the TCGA database, and 98 intersected genes were obtained following Venn diagram analysis." (PMID 34294040, 2021). "EVs-miR-182-5p promotes tumorigenesis and metastasis of breast cancer cells by regulating the CMTM7/EGFR/AKT signaling axis." (PMID 34294040, 2021). "Overall, this study provides new insights into the significant role of CMTM6 and CMTM7 in the regulation of PD-L1 surface expression in breast cancer cells undergoing EMT." (PMID 33803139, 2021). "The RT-qPCR results showed that the expression of CMTM7 was down-regulated in breast cancer tissues compared with adjacent normal tissues." (PMID 34294040, 2021). "Moreover, CMTM7 was also found to serve as a potential biomarker for identifying immunological traits and predicting immunotherapy effectiveness in breast cancer." (PMID 38933262, 2024). "Comparing with other types, the expression of CMTM7 seemed to be higher in basal-like breast cancer type, which is a more aggressive subtype, and might be abnormal for a tumor suppressor should be performed." (PMID 36829181, 2023). "In summary, our study uncovered the existence of the miR-182-5p/CMTM7/CTNNA1/CTNNB1/TCF3 regulation loop in breast cancer, which may provide novel targets and promising strategies for breast cancer therapy." (PMID 36829181, 2023). "Furthermore, a previous study demonstrated the miR-182-5p regulation on CMTM7 in breast cancer, demonstrating that EVs-miR-182-5p promoted tumor progression by regulating the CMTM7/EGFR/AKT signaling axis." (PMID 36829181, 2023). "Among all CMTM members, the CMTM7 expression was significantly lower in breast cancer." (PMID 36829181, 2023). "CMTM7 was found to be significantly downregulated in both breast cancer tissues and cell lines compared with normal breast cancer tissues and cell lines in our study; however, it is interesting that CMTM7 expressed differentially among breast cancer subtypes." (PMID 36829181, 2023). "CMTM7-overexpressed cells exhibited a lower proliferation rate, less colony formation, and a lower EdU positive ratio compared to control cells, indicating that CMTM7 could inhibit breast cancer cell proliferation." (PMID 36829181, 2023).
breast carcinoma (continued). "Finally, the effect of targeting CMTM6 and/or CMTM7 in breast cancer cells undergoing EMT on tumor development, metastasis, and T cell activity should be addressed." (PMID 35575054, 2022). "Taken altogether, our findings demonstrates that EVs secreted by breast cancer cells could carry miR-182-5p to aggravate breast cancer through downregulating CMTM7 expression and activating the EGFR/AKT signaling pathway." (PMID 34294040, 2021). "On the basis of above literature and findings, we proposed the hypothesis that breast cancer cell derived-encapsulated miR-182-5p regulates the CMTM7/EGFR/AKT signaling pathway, thus contributing to the development and progression of breast cancer." (PMID 34294040, 2021). "Therefore, we speculated whether EVs-miR-182-5p can regulate activation of the EGFR/AKT signaling pathway through inhibition of CMTM7, thus promoting breast cancer angiogenesis." (PMID 34294040, 2021). "MiR-182-5p within the extracellular vesicles of BC can specifically target and suppress the expression of CMTM7, activating the CMTM7/EGFR/AKT pathway and facilitating the progression of breast cancer." (PMID 38223763, 2024). "In breast cancer patients, the expression level of CMTM5 and CMTM7 is decreased, while the expression level of CMTM6 is increased." (PMID 38223763, 2024). "We identified a feedback loop with the composition of miR-182-5p, CMTM7, CTNNA1, CTNNB1 (β-catenin), and TCF3, which play essential roles in breast cancer progression." (PMID 36829181, 2023). "A previous study found that the dual knockdown of CMTM6 and CMTM7 observably downregulated the expression of PD-L1 in the breast cancer cell line MCF-7Mes, indicating the potential role of CMTM7 in reflecting the anti-tumor activity of BRCA." (PMID 36568362, 2022). "CMTM6 silencing in mesenchymal breast cancer cells partially decreased PD-L1 expression on their cell surface, while dual targeting of CMTM6 and CMTM7 significantly decreased PD-L1 in these cells." (PMID 33803139, 2021). "In breast cancer tissues, the mRNA expression levels of only CMTM1, CMTM5, CMTM6, and CMTM7 were measured." (PMID 31998718, 2019). "The mRNA expression levels of CMTM5 and CMTM7 were significantly downregulated while those of CMTM1 and CMTM6 were significantly upregulated in breast cancer tissues than in corresponding normal tissues." (PMID 31998718, 2019). "Besides, the co-localization of CMTM7 and CTNNA1 in breast cancer cells was verified using immunofluorescence." (PMID 36829181, 2023). "Then, in order to explore the specific molecular mechanism of CMTM7 participating in breast cancer angiogenesis, we screened out 5102 genes related to CMTM7 expression in the GSE50428 dataset, and predicted 1411 genes co-expressed with CMTM7 through the MEM database." (PMID 34294040, 2021). "Collectively, all our findings suggest that CMTM7 is a novel biomarker that can recognize the immune-hot TME and predict the effective therapeutic response of immunotherapy in BRCA, indicating that measuring the CMTM7 levels of breast cancers could guide the therapeutic schedule." (PMID 36568362, 2022).
lung cancer (5 papers, 2015 to 2024). A malignant neoplasm involving the lung. "For example, knockdown of CMTM7 was observed to impair the process of autophagy and accelerate the development of tumors in lung cancer." (PMID 38933262, 2024). "An immunohistochemistry assay with tissue microarray indicated that CMTM7 is also down-regulated in lung cancer." (PMID 26528697, 2015). "CMTM7 participated in EGFR-AKT signaling in nonsmall-cell lung cancer; knocking down CMTM7 could reduce Rab5 activation, which promoted tumor growth and metastasis." (PMID 36975415, 2023). "However, the contradiction of this finding with other studies and the unclear mechanism of action reflect the complexity of the relationship between CMTM7 and lung cancer, suggesting a need for further research." (PMID 31754330, 2019). "Research into the relationship of the potential tumor suppressor gene CMTM7 with lung cancer has so far focused on NSCLC, and identified a complex association that could exert either a positive or negative effect on tumor cells." (PMID 31754330, 2019). "Moreover, knockdown of CMTM7 delays EGFR internalization and degradation by reducing Rab5 activation in lung cancer cells." (PMID 34281589, 2021).
breast tumors (2 papers, 2022 to 2025). "Like CMTM6, CMTM7 was shown to be a new lead candidate for regulating PD-L1 in breast tumors undergoing EMT." (PMID 40179060, 2025). "Here, we provide our perspective on the involvement of CMTM6 and CMTM7 as new lead candidates for the regulation of PD‐L1 in breast tumors undergoing an epithelial to mesenchymal transition." (PMID 35575054, 2022).
esophageal cancer (2 papers, 2021 to 2024). A primary or metastatic malignant neoplasm involving the esophagus. "Published data showed that CMTM7 was poorly expressed in several tumors, including colorectal cancer, pancreatic cancer and esophageal cancer, involved in the occurrence and metastasis of a variety of tumors." (PMID 34294040, 2021).
gastric cancer (2 papers, 2021 to 2024). A primary or metastatic malignant neoplasm involving the stomach. "CMTM7 has been reported to be down-regulated in gastric cancer and this downregulation facilitates the proliferation and tumorigenesis of gastric cancer cells in vitro and in vivo." (PMID 34294040, 2021). "Thus, SOX10 can regulate cell proliferation and gastric cancer progression by regulating the expression of CMTM7 (Jin, Qin & Jia, 2018)." (PMID 38223763, 2024). "SOX10, a transcriptional regulator of CMTM7, mediates CMTM7 expression in gastric cancer." (PMID 38223763, 2024). "CMTM7, widely expressed in normal gastric tissues, is weakly expressed in gastric cancer tissues." (PMID 38223763, 2024). "CMTM7 has been largely reported to be down-regulated and functions as a tumor suppressor by suppressing the cell proliferation, invasion and migration in vitro and tumorigenesis in vivo in a variety of cancers, including liver cancer and gastric cancer." (PMID 34294040, 2021).
heart failure (2 papers, 2011 to 2020). Inability of the heart to pump blood at an adequate rate to meet tissue metabolic requirements. "There was a GWAS study that reported on a genetic locus polymorphism of the CMTM7 gene that has a significant correlation with European all-cause mortality in patients with heart failure, and can increase the risk of death from heart failure patients." (PMID 32111069, 2020).
liver cancer (2 papers, 2021 to 2022). An epithelial or non-epithelial malignant neoplasm that arises from the liver. "CMTM7 and ORM2 as IRGs, CMTM7 acts as a tumor suppressor by inhibiting cell cycle progression in liver cancer, and ORM2 is closely associated with cancer-promoting pathways for liver cancer." (PMID 36353638, 2022).
triple-negative breast carcinoma (2 papers, 2021 to 2022). An invasive breast carcinoma which is negative for expression of estrogen receptor (ER), progesterone receptor (PR), and human epidermal growth factor receptor 2 (HER2). "In addition, CMTM7 expression was remarkably higher in patients with triple-negative breast cancer (TNBC) (p < 0.0001), a molecular subtype with dead aggressiveness and a lack of effective therapies, but often overexpressing PD-L1 and showing encouraging therapeutic responses to immunotherapy." (PMID 36568362, 2022). "In this research, triple-negative breast cancer (BRCA), a molecular subtype having a lower response to endocrinotherapy but a higher response to chemotherapy and immunotherapy, showed higher transcriptional levels of CMTM7." (PMID 36568362, 2022). "In addition to CMTM6, our in silico data on triple negative breast cancer patients showed a positive correlation between EMT markers and two other members of CMTM family (CMTM3 and CMTM7)." (PMID 33803139, 2021).
cataract (1 paper, 2025). Partial or complete opacity of the crystalline lens of one or both eyes that decreases visual acuity and eventually results in blindness. "A DT model trained on the in vivo dataset (GSE230320), using the genes PLAGL2, CMTM7, NR1D2, and PCYT1B, not only accurately predicted cataracts in the other in vivo dataset but also demonstrated good predictive performance in two separate ex vivo datasets." (PMID 40027191, 2025).
central obesity (1 paper, 2020). "The present study demonstrated a relationship between a novel SNP of CMTM7 rs347134 and weight, BMI, WC, WHtR, SP, odds of general overweight/obesity, and central obesity in Han Chinese male children for the first time, and the GG genotype was a potential risk factor of obesity." (PMID 32111069, 2020).
esophageal squamous cell carcinoma (1 paper, 2021). Esophageal squamous cell carcinoma (ESCC) is a type of esophageal carcinoma (EC) that can affect any part of the esophagus, but is usually located in the upper or middle third. "CMTM7, located on chromosome 3p22.3, is a tumor suppressor gene that is downregulated or absent in many cancer types [such as esophageal squamous cell carcinoma (ESCC) and non-small cell lung cancer (NSCLC)] due to promoter hypermethylation and loss of heterozygosity." (PMID 34281589, 2021).
glioma (1 paper, 2022). A benign or malignant brain and spinal cord tumor that arises from glial cells (astrocytes, oligodendrocytes, ependymal cells). "The result indicated that the levels of CMTM3, CMTM6, CMTM7, CMTM8, and CKLF were much higher in IDH-WT than in IDH-mutated gliomas in the TCGA database (p < 0.001)." (PMID 35252165, 2022). "Results showed that the expression level of CMTM1, CMTM3, CMTM6, CMTM7, CMTM8, and CKLF was elevated in high-grade gliomas (grade III; p < 0.01)." (PMID 35252165, 2022). "In this study, it was found that CMTM6, CMTM7, CMTM8, and CKLF were highly expressed in grade III and IDH-WT gliomas." (PMID 35252165, 2022). "As illustrated, the expression of CMTM3, CMTM6, CMTM7, CMTM8, and CKLF in Grade II and III gliomas showed similar tendency as that in TCGA and CGGA databases." (PMID 35252165, 2022).
hepatocellular carcinoma (1 paper, 2020). A malignant tumor that arises from hepatocytes. "Several members, such as CMTM3, CMTM4, CMTM5 and CMTM7, have been documented to exhibit tumor suppressor functions in hepatocellular carcinoma cells." (PMID 33101541, 2020).
insomnia (1 paper, 2022). A sleep disorder characterized by difficulty in falling asleep and/or remaining asleep. "Tumor suppressor genes, CMTM7, NKAPL and ATM (encoding ATM checkpoint kinase) may allude to aberrant DNA damage responses contributing to insomnia, and indeed, there are several reports of links between DNA damage and sleep in the literature." (PMID 35711912, 2022).
Obesity (1 paper, 2020). Accumulation of substantial excess body fat. "Based on a database search, this is the first study to demonstrate the relationship between the CMTM7 rs347134 polymorphism and obesity, dietary patterns, sleep duration, as well as the interaction between this SNP and particular dietary patterns." (PMID 32111069, 2020). "Our findings indicate for the first time that the GG genotype of CMTM7 rs347134 is potentially a novel obesity risk factor for Han Chinese male children and is associated with dietary patterns more or less." (PMID 32111069, 2020). "Thus, the present study was undertaken to reveal the association and interaction of the CMTM7 rs347134 polymorphism with dietary patterns, physical activity, and sleep duration, and the consequent risk of obesity in Han Chinese children." (PMID 32111069, 2020). "So, these may provide clues for future studies on the relationship between the CMTM7 gene and obesity." (PMID 32111069, 2020). "At present, researches on the CMTM7 gene mainly focus on cancer suppression and immune enhancement, but association or mechanistic studies between CMTM7 and obesity have not been reported anywhere in the world." (PMID 32111069, 2020).